NPM1 (nucleophosmin 1)
Diseases named in the same sentence as NPM1 in open-access papers (continued):
Sharing a sentence is not in itself a finding about the gene and the disease.
tumor (continued). "It is reported that knocking down NPM1 reduced tumor cell survival significantly after radiation." (PMID 36769088, 2023). "NPM1 signalling also regulated tumour cell proliferation, migration, chemotaxis, and invasion." (PMID 37251542, 2023). "Furthermore, the DMF significantly inhibited tumour metastasis induced by the NPM1/ELMO1 signalling pathway, as observed in in vitro cell functional experiments." (PMID 37251542, 2023). "In summary, NPM1 has various options for promoting tumor genesis and function as a proto-oncogene." (PMID 35054502, 2022). "Thus, the double-faced role of NPM1 is reflected in its ability to act as either an oncogene or a tumor suppressor." (PMID 36282861, 2022). "These engineered cells showed strong in vitro and in vivo activity against preclinical models of NPM1-mutated AML cells carrying NPM1-mutant/HLA-A2 complex but not against NPM1 wild-type/HLA-A2+ AML cells or HLA-A2 negative tumor cells." (PMID 36008542, 2022). "The expression of NPM1 is negatively correlated with B cell and macrophages infiltration, which may affect the tumor immunity of ESCA by affecting B cell and macrophages infiltration." (PMID 36188614, 2022). "Finally, NPM1-mutated AML harboring concomitant clonal hematopoiesis driven mutations (e.g., DNMT3A, TET2) showed an enriched tumor inflammation signature score, predicting a clinical benefit from anti-PD-1 treatment." (PMID 36008542, 2022). "Therefore, NPM1 can potentially function as a histone chaperone during DNA strand break repair of tumor cells." (PMID 36428674, 2022). "We believe that patients with gastrointestinal cancer express high levels of NPM1 which may result in immune escape and anti-tumor immunity, suggesting that NPM1 may be important in regulating the immune response to gastrointestinal cancers." (PMID 36188614, 2022). "NPM1 is a multifunctional nucleolar protein that plays an important role in tumour development." (PMID 35735113, 2022). "Finally, NPM1 and tumor immunity, m6A methylation modification, and cuproptosis related genes in ESCA were studied to establish a basis for developing new treatment strategies." (PMID 36188614, 2022). "In summary, NPM1 has a capability to act either as a tumor suppressor or a proto-oncogene, and its actual role may be determined by the balance between its various molecular partners and the level of NPM1 expression." (PMID 35054502, 2022). "NPM1 is closely related to 12 m6A related genes, which may affect the tumor progression of ESCA by affecting the methylation level of m6A." (PMID 36188614, 2022). "Finally, the relationship between NPM1 and tumor immune cell infiltration, m6A and glycolysis related genes was discussed, which is helpful to understand the possible mechanism of LUAD." (PMID 34335635, 2021). "Overexpression of NPM1 can promote the growth and proliferation of various tumor cells." (PMID 34335635, 2021). "Indeed, NPM1 is thought to exert both oncogenic and tumor suppressor roles, since it has been described to be overexpressed, mutated, aberrantly located or even deleted in tumors." (PMID 34885010, 2021). "The expression level of NPM1 in LUAD is significantly related to tumor stage and prognosis." (PMID 34335635, 2021). "However, current studies on the role of NPM1 in tumor mainly focus on its role in ribosome processing and assembly, centrosome replication and molecular chaperone." (PMID 34335635, 2021). "Also, deletions of JAK2, CD274 and MYD88 genes, and amplification of FGFR4 and NPM1 genes, are also involved in clinical trials for other tumor types." (PMID 33668731, 2021). "Active ERKs could therefore also lead to a more tumor‐promoting phenotype via the HIF‐1/NPM1 axis in the hypoxic microenvironment of solid tumors." (PMID 34388291, 2021). "Meanwhile, increasing the expression of NPM1 could attenuate the repression effect of silencing KPNA2 in tumour cells." (PMID 34469024, 2021).
tumor (continued). "Enhanced NPM1 expression has a clear correlation with increased tumor grade and poor prognosis." (PMID 34335929, 2021). "In addition, we explored the difference in the expression of NPM1 in tumor group versus control group at the protein level." (PMID 34899858, 2021). "However, a quantitative dPCR assay using the tumor- and patient-specific NPM1–ALK DNA breakpoint was tested for MDD and MRD measurement." (PMID 33921029, 2021). "We suggest that the high expression of NPM1 in LUAD patients may trigger an anti-tumor immune response, suggesting that NPM1 plays an important role in the immune regulation of LUAD." (PMID 34335635, 2021). "The expression level of NPM1 is closely related to the extent of immune cell infiltration, which may reduce the anti-tumor effect by inhibiting the infiltration of B cells and NK cells." (PMID 34335635, 2021). "Furthermore, NPM1 mutants (NPM1c) acquire the ability to impound the wild-type form, preventing the NPM1 wild-type tumor suppressor functions." (PMID 32188030, 2020). "By GO analysis, the proteins affected by NPM1 cover a large number of proteins with biological functions, which may play an important role in the development of tumor in 492 differential proteins." (PMID 32411234, 2020). "Moreover, DNMT3A, IDH1, IDH2 and TET2 mutations are identified as concomitant to NPM1 mutations, confirming the dynamic interplay among AML tumor suppressors." (PMID 32188030, 2020). "However, as the protein is located in the nucleolus, NPM1 can hardly be monitored as early as to be found as extracellular proteins, which limits its value as a biomarker of tumor in the urine." (PMID 32411234, 2020). "Depending on the cellular context, NPM1 may act both as a proto-oncogene and as a tumor suppressor and its perturbations are often involved in tumorigenesis and cancer progression." (PMID 31307523, 2019). "In our next steps, we plan to evaluate patient and healthy donor samples to identify mutant NPM1 specific T cells followed by functional analysis for anti-tumor cytolytic ability and specificity which may help derive future cell therapy approaches." (PMID 31291378, 2019). "Comparison of APE1 and NPM1 gene expression levels in TCGA tumor datasets." (PMID 31307523, 2019). "More than half of the tumor samples had normal karyotypes; nearly half (6 of 13) bore NPM1 mutation A and most (9 of 13) had FLT3-ITD mutations, likely reflecting the increased frequency of banked tumor specimens from patients with high white blood cell counts." (PMID 31291378, 2019). "We performed whole-exome sequencing (WES) of tumor-normal matched samples of de novo AML-NK patients lacking mutations in NPM1, CEBPA or FLT3-ITD to identify new gene mutations with potential prognostic and therapeutic relevance to patients with AML." (PMID 30303964, 2018). "NPM1 has been ascribed both growth promoting and tumor suppressive functions." (PMID 28045037, 2017). "Obviously, the Kaplan–Meier analysis revealed that individuals with high intra-tumor expression levels of NPM1 had a significantly worse prognosis than those with low intra-tumor expression levels of NPM1, as reflected by the OS and TTR (P = 0.0257 and P = 0.0115, respectively)." (PMID 28874807, 2017). "N6L is an inhibitor of tumor growth and angiogenesis and one of its molecular targets is NPM1." (PMID 26993766, 2016). "However, NPM1 is known to influence ribosome biogenesis, genome stability and tumor suppression and to participate in responses to cellular stresses, including DNA damage, chemotoxicity, and oxidative stress." (PMID 26836305, 2016).
tumor (continued). "Even though the precise mechanism connecting nucleolar breakdown to apoptosis is not clear, data obtained with CIGB-300 support the idea that NPM1 phosphorylation may be a target for cancer treatment in those tumours were high levels of NPM1 are present." (PMID 27058426, 2016). "Considering our observation that lenalidomide could also bind to NPM1, the contribution of these interactions to the anti-tumor effects should be further investigated." (PMID 25617756, 2015). "The ability of NPM1 to suppress apoptosis may play a significant pro-survival role during tumor development." (PMID 26559910, 2015). "Knock-down of NPM1 in Aspc-1 cells slowed the speed of tumor growth in vivo." (PMID 26068981, 2015). "The alteration of NPM1 in human cancer (through overexpression or genetic modification) indicates that NPM1 might play a role as both an oncogene and a tumor suppressor, depending on its dosage and level of expression." (PMID 25663821, 2014). "With IVA, there was four bone-related processes brought front only in the case of the tumour tissue—“myelopoiesis of bone marrow” (NPM1, RARA), “quantity of trabecular bone” (CREBBP, SMO), “outgrowth of bone marrow cells” (ALK) and “inflammatory response of bone marrow-derived macrophages” (RELA)." (PMID 25496518, 2014). "We hypothesized that the NPM1 expression in tumor cells is modulated in response to microenvironmental stimuli." (PMID 24410879, 2014). "Furthermore, knockdown of NPM1 leads to a decrease in the growth of LNCaP-derived tumours grafted in Nude mice in vivo." (PMID 24796332, 2014). "NPM1 seems to play a role as both a tumor suppressor and an oncogene." (PMID 24410879, 2014). "Thus, tumours initiated from NPM1 knocked-down cells remained smaller than control tumours with 85% decrease of the average tumour volume." (PMID 24796332, 2014). "Interestingly, previous studies revealed that NPM1 acts as both tumor suppressor and proto-oncogene during tumorigenesis." (PMID 22631075, 2012). "The level of NPM1 is generally elevated in tumor cells compared with normal cells." (PMID 21152184, 2011). "NPM1 regulates Myc protein turnover as well and may therefore directly impact on cell growth and transformation during tumor development." (PMID 21152184, 2011). "NPM1 is clearly having both growth promoting and tumor suppressive functions." (PMID 21152184, 2011). "The ability of NPM1 to suppress apoptosis and to promote DNA repair may play a significant prosurvival role during tumor development." (PMID 21152184, 2011). "Interestingly, it is now realized that the ARF tumor suppressor promotes SUMOylation of several of its interacting proteins including NPM1." (PMID 21152184, 2011). "NPM1 is acting as a haploinsufficient tumor suppressor in blood cells." (PMID 21152184, 2011). "Furthermore, NPM1 has been shown to regulate tumor suppressor pathways." (PMID 41413654, 2026). "Integration of SNP array, exome, and FISH data was used to infer tumor phylogeny, which indicated that disease pathogenesis was initiated by the TET2 nonsense mutation with subsequent deletion of the second TET2 allele, followed by acquisition of the NPM1 mutation." (PMID 36480300, 2023). "In addition, although intercellular communication between tumour cells and the CXCL12/CXCR4 signalling pathway has been widely studied in tumour chemotactic and metastatic processes in many cancer types, few studies have focused on the effect of NPM1 in CXCL12-mediated HCC chemotaxis and migration." (PMID 37251542, 2023). "An interaction of cohesin proteins with NPM1 could be mediated by CCCTC-binding factor—a transcription factor that regulates tumor suppressor loci—which has been shown to bind and interact with both, potentially contributing to their role in stem cell self-renewal." (PMID 36693840, 2023).
tumor (continued). "NPM1-mutated protein, stably expressed on tumor cells but not on normal tissues, may serve as an ideal target for NPM1-mutated AML immunotherapy." (PMID 37345068, 2023). "However, NPM1 is also positively correlated with the expression of two cuproptosis related genes, which may affect the regulation of cuproptosis in tumor cells by affecting the expression of these genes." (PMID 36188614, 2022). "Different roles for NPM1 may exist in the nucleus and cytoplasm of tumor cells." (PMID 36428674, 2022). "The WRN gene was recognized as a tumor-suppressor gene and evidence suggests that it plays a role in promoting oncogenic proliferation which may likely contribute to AML transformation in Patient 5, in addition to the NPM1 and IDH2 mutations." (PMID 34560908, 2021). "We suggest that ERK‐mediated phosphorylation of HIF‐1α regulates its physical interaction with NPM1, which is essential for the productive association of HIF‐1 with hypoxia target genes and their optimal transcriptional activation, required for survival under low oxygen or tumor growth." (PMID 34388291, 2021). "Finally, NPM1 expression was found to be related to tumor grade." (PMID 34335635, 2021). "Therefore, circWHSC1 targets the miR‐646/NPM1 pathway to exert its role in tumour development." (PMID 32378344, 2020). "Among the proteins of interest (NPM1, FLT3, DNMT3A, IDH1, IDH2, KIT, and RAS), non-mutation bearing ligands from NPM1 were the most frequent in both patient tumor samples and cell lines, including ligands close to or corresponding to where hotspot mutations occur (EAIQDLWQW and MTDQEAIQDLWQWR)." (PMID 31291378, 2019). "Hence, DDX27- NPM1-NF-κB forms a functional axis that cooperatively regulates tumor progression." (PMID 29535419, 2018). "Interestingly, while the nucleolar starvation strategy was initially proposed for the treatment of AML with NPM1c+, evidences obtained so far suggest that could it be effective also in tumours where wild-type NPM1 is overexpressed." (PMID 27058426, 2016). "Interestingly, both NPM1 and HMGAs are highly expressed in tumor cells." (PMID 25711412, 2015). "NPM1 overexpression seems thus to potentiate tumorigenic characteristics of different cancer cell types, and may be an important actor in the evolution of tumours aggressiveness." (PMID 24796332, 2014). "However, NPM1 expression presented a large inter- and intra-tumor heterogeneity, which might complicate the development of diagnostic tests or treatments targeting the NPM1." (PMID 24410879, 2014). "Moreover, how does the growth promoting activities of NPM1 fit with its role as tumor suppressor?" (PMID 21152184, 2011). "Taken together, our data suggest that NPM1 is required for WNT-driven intestinal cell proliferation and tumor initiation; this dependency persists after oncogenic KRAS activation, which drives resistance to epidermal growth factor receptor and mTOR inhibition." (PMID 41413654, 2026). "To conclude, we describe an overarching mechanism whereby NPM1 expression is upregulated upon oncogenic insult and is essential to support WNT-driven hyperproliferation and tumor initiation." (PMID 41413654, 2026). "Upregulation of epigenetic and transcriptional regulators such as NPM1, SMARCA4, ASPSCR1-TFE3 and TFEB further suggests that tumor signals drive transcriptional reprogramming of model immune cells, creating a stable pro-oncogenic phenotype." (PMID 41514627, 2025). "To unravel the downstream oncogenic signaling triggered by secreted HMGA1, we conducted phosphoproteomic analysis, identifying hyperphosphorylation of Nucleophosmin 1 (NPM1), as a pivotal event that further amplifies tumor cell proliferation." (PMID 41145488, 2025). "It is the main nucleolar interaction partner for the p14ARF tumor suppressor and the c-MYC oncoprotein, and knockdown experiments have identified NPM1 as a promising target for cancer therapy." (PMID 36743470, 2023).
tumor (continued). "CSF1R, FGFR1, FLT3, and KDR are related to the tumor microenvironment, and ERBB4, STK11, PTEN, and NPM1 are related to proliferation-related factors." (PMID 36780540, 2023). "These NPM1/HIF‐1α co‐upregulated genes are enriched in three different cancer types, and their expression correlates with hypoxic tumor status and worse patient prognosis." (PMID 34388291, 2021). "Classic examples of this phenomenon are nucleophosmin 1 (NPM1) and PTPRK, putative tumor suppressor genes that are recurrently fused to ALK1 and RSPO3, respectively." (PMID 34585724, 2021). "Immunofluorescence (IF) microscopy showed that NPM1 knockdown promoted CD8+ lymphocyte infiltration and granzyme B secretion in tumor tissues." (PMID 32245950, 2020). "In line with this deduction, tumor-infiltrating lymphocytes were analyzed by flow cytometry, and the CD45+ CD8+ T cell population was remarkably increased in tumors with NPM1 silenced." (PMID 32245950, 2020). "The cBio Portal generated a network showing that ENO1, PTGES3, NPM1 and STMN1 are connected in this tumor." (PMID 29545914, 2018). "NPM1, copy number duplication on chromosome 5 in our study, was overexpressed in primary HCC tissues compared to those in non-tumor tissues." (PMID 28874807, 2017). "In present study, the clinically relevant data presented showed that patients with HCC and high tumor NPM1 expression levels had decreased OS times and earlier TTR compared to those with low tumor NPM1 expression levels." (PMID 28874807, 2017). "We propose that NPM1 participates in the organization of the liquid-like structure of the GC and consequently may actively participate in stress signal integration and transmission, thereby explaining its known roles in ribosome biogenesis, tumor suppression and other processes." (PMID 26836305, 2016). "Taken together, our quantitative proteomic analysis detected the molecular triad, NPM1, GRP78 and RKIP participating together with NCL and HSP27/HSPB1 in a network related to tumor progression." (PMID 26108672, 2015). "A flurry of papers 2008-2009 revealed an intricate series of interactions taking place between NPM1, the ARF tumor suppressor and the SUMO-pathway." (PMID 21152184, 2011). "Furthermore, we examined NPM1 and HMGA1 co-expression in the tumor samples, revealing a notable 20.69% co-expression rate." (PMID 41145488, 2025). "Nucleophosmin 1 (NPM1) is a multifunctional protein that is overexpressed in actively proliferating cells and cancer cells, where it exerts its oncogenic effects by binding and inhibiting various tumor suppressors." (PMID 38662949, 2024). "Though clinical research will be needed to substantiate the utility of immunotherapy in treating NPM1-mutant AML, in vitro models, and a mice model, have shown that CAR-T cell therapies may have anti-leukemic utility while mitigating off-tumor toxicity." (PMID 39200232, 2024). "Eight cases with tumor depth >10 mm showed mutations in CSF1R, ERBB4, FLT3, KDR, and NPM1, regardless of lymph node metastasis." (PMID 36780540, 2023). "Among them, ERBB4 and NPM1 are presumably involved in cSCC tumorigenesis; in addition, GNAQ, GNAS, JAK2, NRAS, IDH2, and CTNNB1 may be related to tumor metastasis." (PMID 36780540, 2023).